PROX1 (prospero homeobox 1)
Diseases named in the same sentence as PROX1 in open-access papers (continued):
Sharing a sentence is not in itself a finding about the gene and the disease.
intestinal cancer (2 papers, 2017 to 2023). "ChIP assay demonstrated that TCF4 binds specifically to the −49 kb region to activate Prox1 expression in intestinal cancer cells, whereas in murine hippocampal NSCs, Prox1 activation requires the binding of TCF/LEF to both the −43 and −49 kb regions." (PMID 37091974, 2023). "In subgroup analysis, PROX1 was a significant marker of better prognosis in patients aged under 66 (p = 0.007), in those with intestinal cancer (p = 0.025), among men (p = 0.019), and in tumors of less than 5 cm diameter (p = 0.030)." (PMID 28854215, 2017). "Among patients with intestinal cancer, those with high PROX1 immunostaining had superior survival." (PMID 28854215, 2017).
Lipedema (2 papers, 2020 to 2022). Disorder of adipose tissue characterized by symmetric and bilateral enlargement of the lower extremities due to abnormal deposition of subcutaneous fat often in obese women. "In this regard, three lymphatic vessel markers (podoplanin/PDPN, LYVE-1 and PROX-1) were used to characterize the size and number of lymphatic vessels in paraffin tissue sections from lipedema and control patients." (PMID 32616854, 2020). "The expression levels of other lymphatic-related genes, such as podoplanin (PDPN), PROX-1, lymphatic-vessel endothelial hyaluronan receptor 1 (LYVE1), and C-C motif chemokine ligand 21 (CCL21), were similar in lipedema fat tissue compared to healthy controls." (PMID 36551837, 2022). "No significant changes were observed for most of the common lymphatic markers, namely PDPN, PROX-1, LYVE-1, CCL21 but a 1.9-fold (P = 0.02) increase was observed in the expression of VEGFR-3 in lipedema in comparison to the control." (PMID 32616854, 2020).
lymphangiosarcoma (2 papers, 2018 to 2025). A malignant neoplasm arising from the endothelial cells of the lymphatic vessels. "Additionally, our findings reveal that SOX18 inhibition by Sm4 results in a decrease in lymphatic phenotype key markers (PROX1, VEGFR3, and LYVE1), indicating a potential role for SOX18 in promoting cancer‐related lymphangiogenesis as well as lymphangiosarcoma development and progression." (PMID 39791369, 2025).
lymphatic malformation (2 papers, 2016 to 2025). Primary lymphedema is caused by anatomic or functional defects in the lymphatic system, resulting in chronic swelling of body parts and lymphatic-system malformation. "PROX-1, on the other hand, plays a key role in the differentiation and maturation of lymphatic vessels and is used to evaluate lymphatic malformations and tumors associated with the lymphatic system." (PMID 40104490, 2025). "In our data, the down-regulation of Prox1 by rapamycin did not affect the proliferation of HepG2 cells, but a recent report showed that the treatment of rapamycin in lymphatic endothelial cells of lymphatic malformations (LM-LEC) diminished cellular proliferation." (PMID 26922671, 2016).
pancreatic ductal adenocarcinoma (2 papers, 2016 to 2025). An infiltrating adenocarcinoma that arises from the epithelial cells of the pancreas. "In conclusion, high PROX1 and β-catenin expression were independent factors for better prognosis in pancreatic ductal adenocarcinoma." (PMID 27411302, 2016). "The aim of this study was to investigate PROX1 and β-catenin expression in pancreatic ductal adenocarcinoma (PDAC)." (PMID 27411302, 2016). "It remains unclear whether the downregulation of PROX1 expression enhances the lymphatic metastatic spread of pancreatic ductal adenocarcinoma." (PMID 27411302, 2016).
sarcoma (2 papers, 2011 to 2019). A usually aggressive malignant neoplasm of the soft tissue or bone. "Indeed we found increased expression levels for RMS-markers (Myog, Myl4, Igf2, Prox1), a FS-gene (Vcan), and LS-related genes (Pparg, Myo1e, Hoxa5, Plau), which further established the MD-tumors as mixed sarcomas consisting of RMS, FS and LS-compartments." (PMID 21533183, 2011). "Amongst sarcomas, PROX1 is highly expressed in rhabdomyosarcoma, which could explain the generally low expression of MMP14 in this sarcoma type." (PMID 31466240, 2019).
Sepsis (2 papers, 2024). Sepsis is defined as life-threatening organ dysfunction caused by a dysregulated host response to infection. "We further showed that CCL21 was colocalized with Prox1 in pulmonary lymphatic vessels and was also reduced notably in sepsis-induced ARDS." (PMID 37971881, 2024). "Western blot analysis revealed that sepsis significantly decreased Lyve-1 and Prox1 levels in the meninges compared to those in the vehicle group, especially at 1 day after LPS injection." (PMID 38287311, 2024). "To observe the pathological changes of pulmonary lymphatic vessels during sepsis, we used inducible Prox1+ LEC-specific lineage-tracing Prox1-CreERT2+Rosa26-tdTomato+ mice." (PMID 37971881, 2024). "Additionally, the percentage area coverage and the relative intensity of pulmonary lymphatic vessels (Prox1-tdTomato+VEGFR-3+/Prox1-tdTomato+CD31+/Prox1+) were overall decreased in LPS/CLP-induced sepsis mice, especially at 24 hours and 48 hours." (PMID 37971881, 2024). "Furthermore, we also detected a significant reduction of pulmonary blood vessels (CD31+Prox1-tdTomato–) and the disruption of vascular endothelial barrier in LPS-induced sepsis mice." (PMID 37971881, 2024). "To investigate whether meningeal lymphatic cells are also damaged by sepsis, we examined the protein levels of Lyve-1, a marker of lymphatic endothelial cells (LECs), and Prox1, a transcription factor that induces lymph angiogenesis, in the meninges." (PMID 38287311, 2024). "We examined pulmonary lymphatic vessels marked with Prox1-tdTomato (red) and VEGFR-3 immunofluorescence (green) at 6 hours, 12 hours, 24 hours, and 48 hours in LPS-induced sepsis mice and found that the diameter of pulmonary lymphatic vessels was increased at 6 hours and decreased subsequently." (PMID 37971881, 2024). "We observed that CCL21 was colocalized with Prox1-tdTomato in pulmonary lymphatic vessels; moreover, the area coverage and the relative intensity of CCL21+ cells were significantly decreased in sepsis, while VEGF-C156S posttreatment could increase LPS-inhibited CCL21 expressions simultaneously." (PMID 37971881, 2024). "Moreover, VEGF-C156S posttreatment increased the percentage area and the relative fluorescence intensities of pulmonary/LN lymphatic vessels (Prox1-tdTomato+VEGFR-3+/Prox1-tdTomato+CD31+) and endothelial integrity in LPS/CLP-induced sepsis mice." (PMID 37971881, 2024).
spindle cell hemangioma (2 papers, 2016 to 2019). Spindle cell hemangioma (SCH), also known as spindle cell hemangioendothelioma, is a rare benign vascular tumor either solitary or multiple, characterized by cavernous blood vessels separated by spindle cells reminiscent of those in KaposiBs sarcoma and located in the dermis and subcutis. "Wang L. reported that, in our case, the endothelial cells in spindle cell hemangioma were positive for CD31 and Prox1, focally positive for D2–40." (PMID 31046794, 2019).
squamous cell carcinoma (2 papers, 2015 to 2025). A carcinoma arising from squamous epithelial cells. "Given that P63 is a well-known marker of squamous differentiation and the basal cell phenotype, these findings might suggest that P63 positivity may be associated with upregulation of PROX1 expression at lower levels, potentially influencing squamous cell carcinoma differentiation." (PMID 40843762, 2025). "According to the results of a recent study, growth and migration of vascular endothelial cells were decreased by the addition of culture supernatant derived from Prox1 siRNA-treated oral squamous cell carcinoma cell cultures." (PMID 25573115, 2015). "The objective of this study is to evaluate the immunohistochemical expression of PROX1 in NSCLC, specifically in the adenocarcinoma and squamous cell carcinoma subtypes, and to assess its correlation with clinicopathologic features and overall survival (OS)." (PMID 40843762, 2025).
squamous cell carcinoma of the thyroid gland (2 papers, 2019 to 2020). "Next, we emphasize the biological processes and genes regulated by PROX1 in CGTH-W-1 cells, derived from squamous cell carcinoma of the thyroid gland." (PMID 32370142, 2020).
vascular tumors (2 papers, 2018 to 2025). "Comparison with other pediatric vascular tumors revealed that the neoplastic cells of KHE expressed Prox1+, CD31+, and CD34+." (PMID 41303262, 2025). "The tumor cells stained strongly for CD31 (a vascular endothelial marker) and were negative for PROX1 (a lymphendothelial marker) consistent with a malignant vascular neoplasm." (PMID 29872503, 2018).
adenoma (1 paper, 2021). A neoplasm arising from the epithelium. "Immunofluorescence analysis confirmed a corresponding decrease in the Lgr5-GFP+ tumor cell area and Sox9+, Prox1+, and Cd24+ adenoma cells in the intestinal sections 18 days after Lef1 deletion." (PMID 34788095, 2021).
allergic rhinitis (1 paper, 2023). Inflammation of the nasal mucous membranes caused by an IgE-mediated response to external allergens. "In mouse models of allergic rhinitis or acute Coronavirus Disease 2019 (COVID-19) infection, Prox1+ VSs were regressed or compromised." (PMID 39196043, 2023).
Anxiety (1 paper, 2018). Intense feelings of nervousness, tension, or panic often arise in response to interpersonal stresses. "Our own data in the present study show a strong negative correlation between the number of Prox1/NeuN-ir cells and the anxiety index." (PMID 30210297, 2018).
Co-infection (1 paper, 2013). "Co-infection with lentivirus expressing RNAi-resistant Prox1 mutant (lenti-Prox1m) reinstated Prox1 expression (top, lanes 5–6), and intracellular CYP7A1 mRNA level also returned to a level comparable to HepG2 cells infected with control lentiviruses (bottom, bars 5–6)." (PMID 23626788, 2013).
colitis (1 paper, 2022). Inflammation of the colon. "Because of our observation that Prox1+/– mice are protected from DSS-induced colitis, we next decided to evaluate the immune cell type responsible for this effect." (PMID 35663931, 2022). "Accordingly, Prox1+/– mice were protected from DSS-induced colitis and microscopic colon analysis showed increased M2 macrophage infiltration." (PMID 35663931, 2022). "We next analyzed the impact of a defective LV over colitis development by using the Prox1+/– mouse model, characterized by dysfunctional lymphatic vessels including leakage of chyle present in the peritoneal cavity; reduced clearance and widespread lymphatic vascular leak." (PMID 35663931, 2022).
colon adenocarcinoma (1 paper, 2024). "Furthermore, Western blotting and IHC analysis demonstrated, PROX1 expression was significantly higher in the human colon adenocarcinoma samples than in its corresponding non-tumor counterparts." (PMID 38244581, 2024).
Encephalocele (1 paper, 2020). A neural tube defect characterized by sac-like protrusions of the brain and the membranes that cover it through openings in the skull. "The 13 weeks of gestation fetus with a vascular structure staining positive for LYVE1, Prox1, and CD31 was a termination of pregnancy because of the combination of omphalocele and encephalocele." (PMID 32516408, 2020).
endometriosis (1 paper, 2023). The growth of functional endometrial tissue in anatomic sites outside the uterine body. "Existing evidence indicate that the density of LYVE‐1 and Prox‐1 positive lymphatic vessels and the lymphatic vessel growth factor in endometriosis tissues of patients with endometriosis, especially intestinal DSIE, are significantly higher than those in normal human intestinal wall tissues." (PMID 37632165, 2023).
Hepatic steatosis (1 paper, 2018). Steatosis is a term used to denote lipid accumulation within hepatocytes. "Depleting HDAC3 or PROX1 in the liver increases hepatic TGs and results in hepatic steatosis." (PMID 30214048, 2018).
Hydrocephalus (1 paper, 2024). Hydrocephalus is an active distension of the ventricular system of the brain resulting from inadequate passage of CSF from its point of production within the cerebral ventricles to its point of absorption into the systemic circulation. "We first induced hydrocephalus in adult Prox1-eGFP reporter mice on day 1 and immediately i.p. treated them with vehicle or Yoda1 daily for four consecutive days." (PMID 38528202, 2024).
hyperlipidemia (1 paper, 2016). "Because it has been well known that the prolonged use of rapamycin may cause unwanted side effects such as hyperlipidemia, we employed rapamycin to induce the up-regulation of triglycerides in HepG2 cells and investigated the effect of rapamycin on the expression of Prox1." (PMID 26922671, 2016).
hypothyroidism (1 paper, 2025). Abnormally low levels of thyroid hormone. "Furthermore, the impact of hypothyroidism on neuronal differentiation was analyzed through the quantification of adult-born granular neurons positive for BrdU and PROX1 markers located in the GL, SGZ, and hilus of the DG." (PMID 40710365, 2025).
influenza infection (1 paper, 2024). "To study the response of lymphatic vessels to influenza infection, we administrated three doses of tamoxifen into Prox1-CreERT2; R26RtdT mice to label the LECs in the lungs, and then we challenged the mice with H1N1 influenza PR8." (PMID 38529320, 2024). "In this study we used the Prox1-CreER mouse line to specifically characterize the dynamic changes of the lymphatic vessels during influenza infection." (PMID 38529320, 2024).
intestinal lymphangiectasia (1 paper, 2022). Dilatation of the intestinal lymphatic system usually caused by an obstruction in the intestinal wall. "Interestingly, intestinal lymphangiectasia is a rare congenital, acquired, or inherited disorder of the lymphatic vessels that involves lymphatic leakage into the intestine, somehow mimicking several of the characteristic seen in the intestine of Prox1+/- mice." (PMID 35663931, 2022).
ischemia (1 paper, 2022). A hypoperfusion of the BLOOD through an organ or tissue caused by a PATHOLOGIC CONSTRICTION or obstruction of its BLOOD VESSELS, or an absence of BLOOD CIRCULATION. "Besides, NRP1 expression was tightly regulated by growth factors, transcription factors, and injury, e.g., tumor necrosis factor-alpha, Prox-1, and ischemia." (PMID 36425469, 2022).
liver cirrhosis (1 paper, 2008). "Our histological analysis detected the neoexpression of Prox1-protein in ductular biliary cells of liver cirrhosis and of CCC." (PMID 18400094, 2008). "Our study shows dysregulation of Prox1 in liver cirrhosis, HCC and CCC, such as neo-expression in cells with biliary epithelial phenotype in liver cirrhosis, and in CCC." (PMID 18400094, 2008). "The induction of the shorter Prox1 mRNA isoform might be related with a neoexpression in a cell population with biliary phenotype in liver cirrhosis and in CCC." (PMID 18400094, 2008). "In liver cirrhosis and HCC several samples showed lower Prox1 mRNA expression compared to the average of the normal liver." (PMID 18400094, 2008).
liver disease (1 paper, 2025). "This suggests that PROX1 can maintain hepatocyte cell identity and prevent liver disease in vivo, with lower levels permitting plasticity and higher levels reducing transformation and transdifferentiation." (PMID 39948437, 2025).
lupus (1 paper, 2025). "Our current study shows an increase in lymphangiogenic factors such as Lyve-1, Pdpn, Prox-1, and Vegfr3 mRNA in our lupus model." (PMID 40651955, 2025).
memory impairment (1 paper, 2020). "We also show ectopic migration of Prox1 granular neurons into the hilus following rmTBI was not prevented by AraC treatment, suggesting this occurrence may not contribute to memory impairments assessed by Barnes Maze testing." (PMID 32958852, 2020).
metastatic prostate carcinoma (1 paper, 2025). A carcinoma that arises from the prostate gland and has spread to other anatomic sites. "Our integrative analysis of metastatic prostate cancer patient tumors, patient-derived xenografts, and cell models determined that PROX1 is upregulated early in the lineage plasticity continuum and progressively increases as tumors lose AR activity." (PMID 40454483, 2025).
mucinous adenocarcinoma (1 paper, 2025). An invasive adenocarcinoma composed of malignant glandular cells which contain intracytoplasmic mucin. "Despite the fact that PROX1 expression did not differentiate between mucinous and non-mucinous adenocarcinomas (p = 0.152), its distribution among defined expression subgroups was significant (p = 0.002)." (PMID 40843762, 2025).
myocardial infarction (1 paper, 2021). Gross necrosis of the myocardium, as a result of interruption of the blood supply to the area, as in coronary thrombosis. "Conditional knockout of Prox1 in Vav1+ compartments revealed that myocardial infarction could promote a significant lymphangiogenic response to improve cardiac function through Vav1+HC and VEGF-C." (PMID 34925642, 2021).
neurocytoma (1 paper, 2023). "In addition, high expression of PROX1 in the nucleus of neurocytoma is correlated with an increase in the ratio of undifferentiated to poorly differentiated cells, suggesting a role for PROX1 in cell proliferation." (PMID 37685269, 2023).
Prediabetes (1 paper, 2021). "Therefore, in this study, for the first time, postprandial changes in plasma metabolites were analysed by GC–MS in nondiabetic men with different PROX1 genotypes up to 5 years prior to prediabetes appearance." (PMID 34209638, 2021).
pulpitis (1 paper, 2025). Inflammation of the dental pulp. "Thus, we can assume that even in the case of infection‐induced reversible pulpitis, LV dynamics similar to those of non‐infectious TPS occur, with transient Prox‐1 expression at the onset, then disappearing during the resolution." (PMID 40277146, 2025).
rectal NETs (1 paper, 2023). "A previous study showed that PROX1 is involved in the progression of rectal NETs, and the high expression of PROX1 is associated with metastases and poorer prognosis." (PMID 37387515, 2023).
retinal degeneration (1 paper, 2025). Degeneration of the retina. "In contrast, no visual recovery was noted in Pde6brd10/rd10 mice infected with AAV2-αProx1 at P60, indicating that AAV2-anti-Prox1-induced retinal restoration requires early intervention, prior to the completion of retinal degeneration." (PMID 40133314, 2025).
retinitis pigmentosa (1 paper, 2025). Retinitis pigmentosa (RP) is an inherited retinal dystrophy leading to progressive loss of the photoreceptors and retinal pigment epithelium and resulting in blindness usually after several decades. "Moreover, adeno-associated viral delivery of an anti-Prox1 antibody, which sequesters extracellular Prox1, promotes retinal neuron regeneration and delays vision loss in a retinitis pigmentosa model." (PMID 40133314, 2025). "Indeed, PROX1 was accumulated in SOX2-positive MG of 79 years-old retinitis pigmentosa (RP) patient retina but not in the MG of 83 years-old healthy donor retina." (PMID 40133314, 2025).
salivary gland carcinoma (1 paper, 2025). A carcinoma that arises from the major or minor salivary glands. "In a retrospective study on 45 cases diagnosed with salivary gland carcinoma, PROX1 and MTA1 immunoexpressions were assessed concerning the different clinicopathologic parameters, disease-free (DFS), and overall survivals (OS)." (PMID 40660330, 2025). "In contrast to low-grade carcinomas, we observed positive IHC expression of PROX1 in high-grade salivary gland carcinomas." (PMID 40660330, 2025). "The current study aimed to investigate the prognostic relevance of PROX1, and MTA1 in salivary gland carcinomas." (PMID 40660330, 2025).
schizophrenia (1 paper, 2020). A major psychotic disorder characterized by abnormalities in the perception or expression of reality. "For example, a study examining the genetic overlap between T2DM and schizophrenia highlighted, among others, PROX1 as a potentially pleiotropic locus." (PMID 32828613, 2020).